LINC00945 (long independently transcribed non-coding RNA 945)
Synonyms: TCONS_00028834
Gene: Long non-coding RNA gene on chromosome 21 (33,057,829 to 33,065,873, forward strand). Ensembl gene ENSG00000232539.
Diseases named in the same sentence as LINC00945 in open-access papers:
LINC00945 is named in the same sentence as 2 diseases in open-access papers, as found by Europe PMC text mining. Sharing a sentence is not in itself a finding about the gene and the disease. The quoted sentences say what the papers report.
glioma (2 papers, 2023 to 2024). A benign or malignant brain and spinal cord tumor that arises from glial cells (astrocytes, oligodendrocytes, ependymal cells). "We interfered with endogenous LINC00945 expression by LINC00945-overexpressing plasmid to elucidate the biological role of LINC00945 in glioma cells in vitro." (PMID 37004060, 2023). "The overexpression of LINC00945 facilitated glioma cell proliferation, epithelial-mesenchymal transition (EMT), migration, invasion, and tumor growth in xenograft tumor models in nude mice." (PMID 37004060, 2023). "In transwell migration and invasion assays, we observed increased migratory and invasive glioma cells in the LINC00945 overexpression group." (PMID 37004060, 2023). "To investigate the role of LINC00945 in glioma, we detected LINC00945 expression in human glioma and normal brain tissue from our cohort." (PMID 37004060, 2023). "Compared with HEB, LINC00945 in various glioma cells showed highly expressed." (PMID 37004060, 2023). "The results revealed that the high expression of LINC00945 was specific in glioma." (PMID 37004060, 2023). "To further explore the expression mechanism of LINC00945 in glioma, we selected five glioma patient-derived GSCs to profile the landscape of active enhancers, based on the fact that the rank ordering of SE-LINC00945 in GSCs ChIP-seq data of these five patients was in the top 5 of 43 glioma patients." (PMID 37004060, 2023). "Moreover, we verified the epigenetic activation mechanism of LINC00945 via the ChIP assay, and its effect on glioma was determined by performing the functional assay and a mouse xenograft model." (PMID 37004060, 2023). "In addition, the high expression of LINC00945 is specific in gliomas, and LINC00945 has the highest regression coefficient value in our prognostic model, indicating that it contributes the most to the model." (PMID 37004060, 2023). "Additionally, overexpression of LINC00945 promoted glioma cell proliferation, EMT, migration, and invasion in vitro and xenograft tumor formation in vivo." (PMID 37004060, 2023). "Furthermore, we explored the epigenetic activation mechanism of LINC00945 and its effect on glioma." (PMID 37004060, 2023). "Thus, we explored the potential expression mechanism and function of LINC00945 in gliomas." (PMID 37004060, 2023). "The colony-forming assay showed that overexpression of LINC00945 increased the colony-forming ability of both LN18 and PN12 glioma cells." (PMID 37004060, 2023). "Subsequently, based on the results of functional experiments and the mouse xenograft model, we verify that LINC00945 promotes proliferation, EMT, migration and invasion of glioma cells, and tumor growth in vivo, suggesting that LINC00945 may serve as a novel underlying therapeutic target for glioma." (PMID 37004060, 2023). "Overexpression of LINC00945 promoted proliferation, EMT, migration, and invasion of glioma cells." (PMID 38566153, 2024). "In addition, the expression levels of LINC00945 in normal human astrocyte (HEB), human glioma cell lines (LN18, SF126, SNB19, U251, and T98G), and human GBM cell PN12 derived from surgical specimens were measured." (PMID 37004060, 2023).
tumor (1 paper, 2023). "The size of tumor xenografts in the LINC00945 overexpression group was obviously bigger compared to the vector group, and tumor weight in the LINC00945 overexpression group is also heavier." (PMID 37004060, 2023). "In addition, expression levels of LINC00945 in nude mice tumor tissues were significantly increased in the LINC00945 overexpression group than in the vector group." (PMID 37004060, 2023).